PARP1 (poly(ADP-ribose) polymerase 1)
Diseases named in the same sentence as PARP1 in open-access papers (continued):
Sharing a sentence is not in itself a finding about the gene and the disease.
gastric cancer (continued). "Moreover, leaved caspase-3, and cleaved PARP-1, a hallmark of apoptosis, were found significantly increased in the SBCCC treated gastric cancer cells compared to the controls." (PMID 30988662, 2019). "PARP1 inhibition by Olaparib or PARP1 siRNA could significantly attenuate growth and colony formation of gastric cancer cells, and which were mediated through induction of G2/M cell cycle arrest but not apoptosis." (PMID 26540566, 2015). "In the present study, by performing combined analysis of experimental and clinical data, we could demonstrate that PARP1 and FOXO3A are functionally linked and their expression levels are useful in predicting clinical outcomes of gastric cancer patients." (PMID 26540566, 2015). "Our observation may imply that gastric cancer patients carrying defects in POLB function may be stratified for PARP1 inhibitor treatment, resulting in a more effective option." (PMID 26090616, 2015). "By performing cell culture experiments, we could observe that PARP1 inhibition significantly attenuated gastric cancer cell growth, and which were mediated through FOXO3A expression." (PMID 26540566, 2015). "In conclusion, we suggest that PARP1 and FOXO3A play critical roles in gastric cancer progression, and might have therapeutic and/or diagnostic potential in clinic." (PMID 26540566, 2015). "Therefore, we suggest that PARP1 inhibition by Olaparib can suppress the growth of human gastric cancer cells." (PMID 26540566, 2015). "Here, we investigated the effect of PARP1 inhibition in the growth of gastric cancer cells." (PMID 26540566, 2015). "Furthermore, by performing tissue microarrays on the 166 cases of gastric cancer patients, we demonstrated the prognostic predictability of the expression status of PARP1 and FOXO3A in gastric cancer." (PMID 26540566, 2015). "METTL3 can also promote oxaliplatin resistance of gastric cancer (GC) cells by promoting the stability of PARP1 mRNA." (PMID 41194259, 2025). "Hence, these PARP1-mediated effects are thought to aid tumour initiation in gastric cancer." (PMID 34440228, 2021). "Both in vitro and in vivo experiments have demonstrated that CD133+ stem-like cells represent a prominent subpopulation within gastric cancer, and the gene poly[ADP-ribose] polymerase 1 (PARP1) plays a central role in mediating resistance to oxaliplatin." (PMID 41517663, 2026). "PARP1 activates the base excision repair pathway to promote DNA damage repair, resulting in resistance of CD133+ gastric cancer stem cells to oxaliplatin." (PMID 39678510, 2024). "In gastric cancer cells, METTL3 introduces m6A to the 3′‐UTR region of the PARP1 mRNA where the reader YTHDF1 is recruited; this increases its stability and expression." (PMID 39661414, 2024). "Our analysis indicated that PARP1 expression was negatively correlated with the expression of ISGs (IRF7 and ISG15) in human stomach cancer (n = 407 samples, P < 0.01), which is consistent with our in vitro study observations." (PMID 36624848, 2022). "Inhibition of PARP1 induced nuclear localization of FOXO3, which had an anti-proliferative effect on gastric cancer cells." (PMID 29784019, 2018). "In order to explore the role of MTP18 in DOX-induced apoptosis, we determined the extent of doxorubicin induced apoptosis in gastric cancer AGS cells by detecting the levels of cleavage of procaspases including caspase-3 and PARP1." (PMID 28915614, 2017).
gastric cancer (continued). "Survival analyses using tissue microarrays have successfully demonstrated that the expression of PARP1 and FOXO3A are independent prognostic indicators (OS and RFS) for gastric cancer patients." (PMID 26540566, 2015). "In conclusion, our results from cell culture experiments and clinical data analysis consistently indicate that the expression of PARP1 and FOXO3A play pivotal roles in gastric cancer progression." (PMID 26540566, 2015). "Undoubtedly, PARP1 and FOXO3A can be new prognostic and therapeutic targets for gastric cancer management." (PMID 26540566, 2015). "Likewise, poly (ADP-ribose) polymerase 1 (PARP1) induces stemness and taxol resistance by promoting YAP dephosphorylation and its nuclear translocation in gastric cancer cells." (PMID 38607003, 2024). "Furthermore, studies have also shown that alterations in the expression and activity of certain enzymes involved in DNA repair, such as PARP1 and FEN1, can contribute to the development of genomic instability in gastric cancer." (PMID 38127056, 2023). "Gastric cancer patients with H. pylori infection were demonstrated to express higher levels of PARP1 when compared to H. pylori negative gastric cancer patients." (PMID 34440228, 2021). "Additionally, knockdown of ATF4 expression greatly impaired BTZ augmented DDP‐induced PARP1 cleavage, indicating that BTZ enhanced the toxicity of DDP in gastric cancer cells depending on ATF4‐activating apoptosis." (PMID 34709767, 2021). "Using both the PARP1 inhibitor, Olaparib, and OXA in combination effectively inhibited the viability, size, cell count, and proliferation of the organoids derived from the OXA resistance gastric cancers (rGC1 and rGC2) (P < 0.05)." (PMID 34497808, 2021). "In line with this, biglycan was recently shown to modulate gastric cancer aggressive features as cell survival, migration, and angiogenesis and biglycan knockout gastric cancer cells showed increased levels of PARP1 (Poly [ADP-ribose] polymerase 1) and Caspase 3 cleavage." (PMID 34917515, 2021). "PARP1 expression level was significantly higher in colorectal and gastric cancer tissues than that in respective non-tumor tissues." (PMID 33112558, 2020). "Our results may provide new biological and clinical insights on the expressions of PARP1 and FOXO3A in gastric cancer progression." (PMID 26540566, 2015). "In addition, we have addressed clinical utilities of PARP1 and FOXO3A expression for gastric cancer patients." (PMID 26540566, 2015). "Confirming the biological relevance of the PARP1 and FOXO3A expression in gastric cancer cells, we next evaluated the clinical significance of these genes by performing tissue microarray assays in the 166 cases of gastric cancer patients." (PMID 26540566, 2015). "Considering the functional link between PARP1 and FOXO3A, we next sought whether the combined expression status of PARP1 and FOXO3A is better in predicting clinical outcomes of gastric cancer patients." (PMID 26540566, 2015). "This may imply that the Olaparib treatment might be beneficial especially to the BRCA-impaired gastric cancer patients, although further studies might be required to delineate the functional roles of BRCA genes to PARP1 and FOXO3A signaling." (PMID 26540566, 2015). "FOXO3A expression was induced by PARP1 inhibition, suggesting that FOXO3A might be one of downstream target of the PARP1 effect on gastric cancer cell growth." (PMID 26540566, 2015). "We demonstrated that PARP1 inhibition induce G2/M cell cycle arrest but not apoptosis in gastric cancer cells." (PMID 26540566, 2015). "With respect to these, in the present study, we aimed to investigate whether the expressions of PARP1 and FOXO3A have functional and clinical significance in gastric cancer." (PMID 26540566, 2015).
gastric cancer (continued). "PARP1 altered group was substantially correlated with higher immune infiltrates across most tumors, including CD8+ T cells in colorectal adenocarcinoma (P = 0.0061), endometrial carcinoma (P = 0.0033), stomach cancer (P = 0.033), and cervical cancer (P = 0.026), respectively." (PMID 34531868, 2021). "Furthermore, after knockdown of USP47 by RNA interference, we analyzed in gastric cancer cell lines metabolic activity/viability in an MTT assay, and apoptotic cell death by Annexin V staining and poly(ADP-Ribose) polymerase (PARP)-1, caspase 3, and caspase 8 cleavage, respectively." (PMID 29786670, 2018). "Therefore, we could suggest that the PARP1 and FOXO3A expressions are significantly helpful in predicting clinical outcomes of gastric cancer patients." (PMID 26540566, 2015). "Moreover, to our knowledge, the functional and clinical roles of PARP1 in gastric cancer were not evaluated vigorously yet." (PMID 26540566, 2015).
colon carcinoma (63 papers, 2009 to 2026). "In MC-38-induced colon cancer models, PARP-1-deficient mice showed accelerated tumor growth and reduced Th1 and CD8+ T cell response, suggesting that PARP-1 in macrophages regulates Th1 cell response to tumor." (PMID 35906622, 2022). "We observed the activation of caspase 3 in both the colon cancer cell lines that were investigated after 24 h of treatment with the SeNps, as well as the cleavage of PARP1 to its characteristic 89 kDa fragment, which is associated with apoptosis in HT29 cells." (PMID 34771499, 2021). "BRCA1-associated RING domain protein 1 (BARD1) splice variant (SV), BARD1β, can sensitize colon cancer cells to poly ADP ribose polymerase 1 (PARP-1) inhibition by impairing BRCA1 mediated DNA homologous recombination repair." (PMID 32010626, 2019). "Other authors reported that a stable PARP1 knock-out triggers loss of telomere repeats and DDR induction in colon cancer cells." (PMID 36864251, 2023). "Studies of RPL3 in a human colon cancer cell line indicate that RPL3 binds to the nuclear DNA binding protein poly ADP-ribose polymerase 1 (PARP-1) and represses the transcription of pro-invasive genes (Pecoraroet al., 2019)." (PMID 38628976, 2023). "The KRG extract induced apoptosis, as evidenced by the formation of apoptotic cells, an increase in the number of sub-G1-phase cells, and an increase in the levels of cleaved caspase-9, caspase-3, and PARP1 in colon cancer cells." (PMID 36079818, 2022). "In colon cancer, PARP1 is often overexpressed, which indicates its beneficial functional role for β-catenin transcriptional activity." (PMID 34725336, 2021). "In ovarian, lung, and colon cancer cell lines, PARP1 downregulates PD-L1 expression by ADP-ribosylating STAT3 and, thus, decreasing its phosphorylation." (PMID 34725336, 2021). "Although this study endeavors to delineate the mechanisms of how transgelin and PARP1 interaction influences the Rho signaling pathway and participates in colon cancer metastasis, a proper understanding of these mechanisms warrants more comprehensive analysis." (PMID 32774160, 2020). "In summary, we show that colon cancer cells which express BARD1β SV display impaired HR DNA repair and are more sensitive to PARP-1 inhibition." (PMID 27197561, 2016). "BARD1β sensitizes colon cancer cells to poly ADP ribose polymerase 1 (PARP-1) inhibition even in a FL BRCA1 background." (PMID 27197561, 2016). "In colon tumors the PARP-1 mRNA level was higher than in unaffected colon tissue and in polyp tissues." (PMID 25526641, 2014). "Morphometric measurements of colon sections have shown that colon tumor tissue contained about three times greater amount of PARP-1 protein than unaffected colon tissue (mean 6.4, range 3.80–9.0 in tumor versus 2.4, range 1.0–4.0 in normal colon, p<0.00001)." (PMID 25526641, 2014). "Western analysis confirmed an increased amount of PARP-1 in colon tumors in relation to normal colon, but also revealed that anti-PARP-1 antibody reacted also with other proteins, which were particularly abundant in tumor tissue." (PMID 25526641, 2014). "This contrasts to earlier data showing correlation of PARP activity with PARP-1 protein expression in five colon cancer cell lines." (PMID 19568233, 2009). "The mRNA and protein levels of PARG, PARP1, and NF-κB p65 were downregulated by BXD, suggesting that BXD may suppress the malignant characteristics of colon cancer cells by modulating the PARG/PARP1/NF-κB signaling pathway." (PMID 41305005, 2025). "Importantly, PARP1, a major parthanatos inducer, is overexpressed in human tumor-derived colon cancer cells compared to normal intestinal epithelium and promotes colon cancer in mice." (PMID 39979285, 2025).
colon carcinoma (continued). "Regarding colon cancer, lycopene induces apoptosis in HT-29 cell line due to a decrease in the expression levels of procaspases-8, -3 and -9, as well as PARP-1 and B-cell lymphoma 2 protein (Bcl-2), accompanied by an enhancement in Bcl-2-associated X-protein (Bax) expression." (PMID 39334719, 2024). "Furthermore, PARP-1-/- mice exposed to the NOC-related compound AOM develop a higher number of colonic tumors and liver nodules." (PMID 36902118, 2023). "The role of TAGLN in CRC is vaguely describe, though one study showed that it could bind to PARP1 which involved in Rho signalling, therefore, inducing metastasis of colon cancer cells." (PMID 37476187, 2023). "While, blocking PARP1 activity significantly rescued colon cancer from death." (PMID 35715817, 2022). "In addition, we found that celastrol impaired the ability of colon cancer cells to repair DNA by reducing the expression of both PARP1 and BRCA1 genes." (PMID 35326523, 2022). "In the human colon cancer cell line HCT116, rhythmic repressive Lamina Associated Domains (LADs) were shown following the interaction between PARP1 (Poly (ADP-Ribose) Polymerase 1), a chromatin modifier and integrator of feeding with the circadian clock, and CTCF." (PMID 34572096, 2021). "Our results suggest that transgelin binds to PARP1 and regulates the expression of downstream key genes, which are mainly involved in the Rho signaling pathway, and thus participates in the metastasis of colon cancer." (PMID 32774160, 2020). "The variation of the repetition rate of the proton bunches produced an oscillation of the radio-induced cell susceptibility in human colon carcinoma HCT116 cells, which appeared to be related to the presence of the PARP1 protein and an efficient parylation process." (PMID 31300704, 2019). "Thus genetic deletion of Sam68 and PARP1 inhibition exhibited similar effects on reducing colon tumor development in Apcmin716/+ mice, which supports the essential roles of Sam68 and PARP1 in mouse tumor growth in vivo." (PMID 27458801, 2016). "Moreover, genetic deletion of Sam68 and inhibition of PARP1 markedly reduces the development and survival of colon tumors in Apcmin716/+ mice, further supporting the pivotal role of Sam68-conferred PAR-dependent NF-κB activation in colon tumorigenesis." (PMID 27458801, 2016). "Furthermore, Sam68 knockout and PARP1 inhibition both attenuates colon tumor development in Apcmin716/+ mice." (PMID 27458801, 2016). "We sought to examine whether down-regulation of PARP1 or NF-κB transactivation executes a similar function as down-regulation of Sam68 on human colon cancer cell survival." (PMID 27458801, 2016). "Importantly, down-regulation of PARP1 or p65 sensitized colon cancer cells to undergo spontaneous apoptosis, which mirrors the effects of PARP1 inhibition and Sam68 knockdown." (PMID 27458801, 2016). "Also, our reported results showing that an inhibitor of PARP1 (ABT-888) sensitizes colon cancer cell lines to irinotecan have lead to an ongoing clinical trial (clicaltrials.gov, Abbvie, NCT02305758)." (PMID 26257651, 2015). "Moreover, it was demonstrated that PARP-1 plays a role in colon cancer development since its expression was significantly higher in colon cancer and was correlated with tumor size and histopathology." (PMID 25526641, 2014). "In conclusion, osthole-induced human colon cancer cell death may mediate by ROS generation, which subsequently induces Bax/Bcl-2 turnover and promotes caspase-3 activation and PARP-1 cleavage, resulting in cell apoptosis." (PMID 25013761, 2014). "Caspase-dependent apoptosis with inactivation of PARP1 has also been observed after treatment of human lymphoblastoid TK6 cells with digallic acid obtained from Pistacia lentiscus fruits or human colon cancer HCT-116 cells treated with green coffee bean extract (chlorogenic acid complex)." (PMID 30171426, 2018).